H2AX (H2A.X variant histone)
Diseases named in the same sentence as H2AX in open-access papers (continued):
Sharing a sentence is not in itself a finding about the gene and the disease.
Hypertension (3 papers, 2012 to 2023). The presence of chronic increased pressure in the systemic arterial system. "The fact that six of the seven patients in our study with the highest γ-H2AX foci/cell had hypertension points toward an association of γ-H2AX formation/DSBs in the pathogenesis of hypertension." (PMID 23029205, 2012). "Our survey of γ-H2AX formation over a spectrum of clinical diseases including those with environmental stressors such as vitamin D deficiency and those with a strong genetic component such as hypertension supports a role for increased DNA damage in the morbidity of age-related diseases." (PMID 23029205, 2012). "Since disease prevalence in general rises with increasing age (hypertension, for example has only a 6 percent prevalence rate before age 35 but rises in a linear fashion to 78% in those 75 and older) we would expect a concurrent rise in γ-H2AX foci (upward arrows and solid line)." (PMID 23029205, 2012). "Among patients ≥57 y/o, we found a significant (p = 0.037) 36% increase in the number of γ-H2AX foci/cell for patients with hypertension compared to non-hypertensive patients." (PMID 23029205, 2012). "Our results show that hypertension and the FDR of gamma-H2AX foci, which may reflect individual radiosensitivity, are significant predictive factors for the risk of late GI/GU toxicity, such as radiation proctitis and cystitis following radiotherapy for cervical, vaginal and anal cancers." (PMID 37839163, 2023).
infertile (3 papers, 2021 to 2024). "In our experimental setup, we used heterozygous H2AX zygotes, with oocytes from H2AX-KO female mice and sperm from wild-type male mice because H2AX-KO male mice are infertile." (PMID 38744857, 2024). "Consistent with previous studies, our H2AX-KO male mice were also infertile." (PMID 38744857, 2024). "Also, compared with H2ax KO leading to infertility, circSRY KO reduced H2AX level, leading to a lower number of sperm, which is a much milder phenotype that is more challenging to demonstrate clear rescue in vivo." (PMID 36414375, 2023).
lung fibrosis (3 papers, 2022 to 2025). "The H2afx, also known as H2ax, has been proven to be a marker to distinguish patients with or without liver and lung fibrosis and marrow fibrosis." (PMID 35495761, 2022).
myocardial infarction (3 papers, 2020 to 2025). Gross necrosis of the myocardium, as a result of interruption of the blood supply to the area, as in coronary thrombosis. "The attenuation of H2AX was correlated with improvements in cardiac performance, a reduction in the myocardial infarct size, and lessened mitochondrial injury in the I/R model." (PMID 39257436, 2024). "Consistently, the LV myocardial infarct area and the γ-H2AX+ cells exhibited a similar pattern of fibrosis among the four groups." (PMID 32867392, 2020). "Masson's trichrome staining and TTC assay elucidated the myocardial infarction extent, revealing minimal infarct sizes in both the sham-NC and sham-H2AX inhibitor groups, with no discernible differences." (PMID 39257436, 2024).
oral squamous cell carcinoma (3 papers, 2022 to 2023). "Specifically, SNHG17 upregulates PAX6 to facilitate the development of oral squamous cell carcinoma, stimulates SOX4 to promote the epithelial-mesenchymal transition in ESCC cells, and activates H2AX-associated signaling pathways to promote the development of renal cell carcinoma." (PMID 37231440, 2023).
skin cancer (3 papers, 2012 to 2024). "Additionally, p38 MAPK serves as the precursor kinase for Mitogen and Stress Activated protein Kinase (MSK1) and phosphorylated H2AX (γ-H2AX), both of which play a role in the development of UVB-induced skin cancer." (PMID 38566927, 2024).
Alzheimer disease (2 papers, 2019 to 2020). A progressive, neurodegenerative disease characterized by loss of function and death of nerve cells in several areas of the brain leading to loss of cognitive function such as memory and language. "In addition, in Alzheimer’s disease (AD) patients, H2A histone family member X (H2AX) was seen to be phosphorylated more as compared to control, further alluding that hippocampal astrocytes are epigenetically regulated." (PMID 33327654, 2020).
cholangiocarcinoma (2 papers, 2020 to 2025). A carcinoma that arises from the intrahepatic biliary tree (intrahepatic cholangiocarcinoma) or from the junction, or adjacent to the junction, of the right and left hepatic ducts (hilar cholangiocarcinoma). "The positive expression of γ-H2AX was previously reported in precancerous lesions such as BilIN as well as cholangiocarcinoma in patients with hepatolithiasis and occupational cholangiocarcinoma." (PMID 33369464, 2020). "Furthermore, γ-H2AX and S100P expressions were detected in all BilIN lesions in patients with subsequent cholangiocarcinoma." (PMID 33369464, 2020). "All five patients who developed subsequent cholangiocarcinoma had BilIN or IPNB lesions, and the positive expressions of γ-H2AX and S100P were detected in the BilIN lesions of four patients." (PMID 33369464, 2020).
chronic hepatitis (2 papers, 2013 to 2021). An active inflammatory process affecting the liver for more than six months. "It has been reported that tissue samples of ulcerative colitis and chronic hepatitis, both widely known as chronic inflammatory diseases predisposing patients to cancer, overexpressed γ-H2AX." (PMID 34372868, 2021). "In this study, we found that γ-H2AX was sequentially increased from normal to chronic hepatitis and liver cirrhosis." (PMID 23533353, 2013). "Immunohistochemical analysis showed that the LI of γ-H2AX in chronic hepatitis and liver cirrhosis was increased compared with normal livers (chronic hepatitis, 27.5 ± 15.8%, range from 5.0 to 59.3%, P < 0.005; liver cirrhosis, 56.2 ± 31.4%, range from 7.2 to 63.0%, P < 0.005, resp)." (PMID 23533353, 2013).
chronic myelogenous leukemia (2 papers, 2021 to 2025). "γ-H2AX was down-regulated in imatinib-resistant chronic myeloid leukemia cells." (PMID 34781823, 2021).
co-infection (2 papers, 2016 to 2023). "In both HeLa and 293 cells, AAV2 and Ad co-infection induces the phosphorylation of ATM, DNA-PKcs, RPA32, and H2AX." (PMID 36719192, 2023). "Furthermore, co-infection by HSV-1 and HSV-2 resulted in robust levels of γH2AX that were not diminished by PAA, revealing that HSV-2 infection does not elicit active repression of H2AX phosphorylation." (PMID 26817608, 2016).
colon adenoma (2 papers, 2013 to 2016). An adenoma that arises from the colon. "Tumors developed in both WT and Sesn2-/- mice displayed classical characteristics of colon adenomas, such as nuclear β-catenin staining, increased cell proliferation (PCNA staining), DNA damage (γ-H2AX staining) and apoptotic cell death (TUNEL staining)." (PMID 26913956, 2016).
colorectal adenocarcinoma (2 papers, 2022 to 2024). The most common type of colorectal carcinoma. "A retrospective study of patients with colorectal adenocarcinoma could show, that higher γ-H2AX expression levels in the resected specimen could be detected within the tumors with low treatment response following chemoradiotherapy compared to tumors with high regression." (PMID 38502354, 2024).
combined immunodeficiency (2 papers, 2015 to 2017). A broad classification of inherited disorders presenting at birth that affect both the cell-mediated and humoral aspects of the immune response. "In other settings, the results of a clonogenic survival assay in primary skin fibroblasts derived from pediatric severe combined immunodeficiency (SCID) patients were in concordance with the DNA double-strand break repair efficiency measured by the γ-H2AX foci assay." (PMID 29077012, 2017).
cutaneous melanoma (2 papers, 2022 to 2024). A primary melanoma arising from atypical melanocytes in the skin. "DNA damage in plantar melanoma was more frequent in the marginal region, whereas skin melanoma of the upper body showed a sporadic distribution of cells labeled with gamma-H2AX antibody irrespective of location." (PMID 35468978, 2022).
diffuse large B-cell lymphoma (2 papers, 2013 to 2018). "Phosphorylation of cdc25c and H2AX was constitutively detected in diffuse large B-cell lymphoma (DLBCL)." (PMID 29861856, 2018).
folate deficiency (2 papers, 2017 to 2023). A nutritional condition produced by a deficiency of FOLIC ACID in the diet. "Associated with H2AX phosphorylation, folate deficiency has an impact on H3 methylation, which is an indicator for heterochromatin." (PMID 28786938, 2017). "Folate deficiency increases the expression of (phosphorylated H2AX) γ-H2AX, a DNA injury marker protein, as well as the methylation frequency of CpG site in the DSBR gene Rad54 promoter region, and downregulates the expression of Rad54 in mouse sperm and spermatocyte line with folate deficiency." (PMID 36768542, 2023). "Conversely, this long lasting (over weeks) existing γ-H2AX formation may indicate that DSBs induced over weeks of folate deficiency could not further be repaired in the recovery phase." (PMID 28786938, 2017).
HCMV infection (2 papers, 2011 to 2024). "Thus, ATM and H2AX phosphorylation occur early during HCMV infection and both IE1 and IE2 have the capacity to promote these events." (PMID 21589897, 2011).
Huntington disease (2 papers, 2010 to 2016). Huntington disease (HD) is a rare neurodegenerative disorder of the central nervous system characterized by unwanted choreatic movements, behavioral and psychiatric disturbances and dementia. "If a similar loop were operating in cells expressing expanded polyglutamine proteins one might expect to find ROS-mediated DNA damage leading to activation of ATM and phosphorylation of histone H2AX, as has indeed been documented in cells from Huntington's disease and SCA-2 patients." (PMID 20885783, 2010).
invasive breast carcinoma (2 papers, 2016 to 2022). A carcinoma that infiltrates the breast parenchyma. "Using multiple publicly available datasets, we found a significantly strong positive correlation between H2AX expression levels in patients with invasive breast cancer, and levels of glycolysis genes, particularly HK2." (PMID 35260660, 2022).
ischemia (2 papers, 2010 to 2024). A hypoperfusion of the BLOOD through an organ or tissue caused by a PATHOLOGIC CONSTRICTION or obstruction of its BLOOD VESSELS, or an absence of BLOOD CIRCULATION. "Rac GTPase inhibition through administration of NSC23766 resulted in an almost complete attenuation of the oxidative stress damage as indicated by a strong attenuation of 4-HNE, 8-OHdG and p-H2AX immunostaining in the hippocampal CA1 region as compared to saline (ischemia) controls." (PMID 20830300, 2010).
kidney damage (2 papers, 2022 to 2025). "Senescence (p16 and p21) and DNA damage markers (γ-H2AX (ser139)) were assessed in ADR-induced nephropathy." (PMID 40108127, 2025).
laryngeal carcinoma (2 papers, 2016). Carcinoma that arises from the laryngeal epithelium. "Our data suggest that inherent DDR pathway activation (measured by the end-point of phosphorylation of H2AX) is a valuable prognostic marker in patients with laryngeal carcinoma who received preservation approaches." (PMID 27166270, 2016).
liposarcoma (2 papers, 2018 to 2022). A usually painless malignant tumor that arises from adipose tissue. "In conclusion, trabectedin radiosensitizes STS cells by affecting SF (particularly in leiomyosarcoma and liposarcoma), invasiveness, cell cycle distribution, and γ-H2AX foci formation." (PMID 36430780, 2022). "Conversely, liposarcoma cells derived from a radiosensitive tumour had high H2AX but relatively lower SCE levels that may imply inefficient DNA DSB repair." (PMID 29853780, 2018).
liver cirrhosis (2 papers, 2013 to 2014). "The γ-H2AX labeling indices were 1.3 ± 4.13 (mean ± SD) (range, 0 ~ 15.0) in liver cirrhosis, 2.4 ± 5.67 (0 ~ 21.3) in low-grade DNs, 4.1 ± 10.42 (0 ~ 40.2) in high-grade DNs, and 10.3 ± 17.00 (0 ~ 49.0) in HCC." (PMID 24885363, 2014). "Intriguingly, dysplastic nodules showed a significantly increased γ-H2AX expression (74.1 ± 22.1%, range from 20.1 to 94.0%), which was significantly increased compared with those in liver cirrhosis (P < 0.005) and HCC (P < 0.005)." (PMID 23533353, 2013). "γ-H2AX labeling index in HCC was significantly higher than that in normal liver, liver cirrhosis, low-grade DNs, and high-grade DNs (all, P < 0.05)." (PMID 24885363, 2014). "Western blotting detected γ-H2AX in 3 (37.5%) of 8 liver cirrhosis patients with no evident HCC occurrence, while 9 (75%) of 12 HCC cases showed a detectable protein band for γ-H2AX in the adjacent nontumorous liver tissues." (PMID 23533353, 2013). "Moreover, the mean LI of γ-H2AX in nontumorous tissues from HCC patients with liver cirrhosis was significantly increased when compared with the cases with liver cirrhosis without HCC (62.5 ± 24.7%, range from 5.1 to 96.0%, P < 0.005)." (PMID 23533353, 2013). "Moreover, γ-H2AX was significantly increased in nontumorous tissues of HCC as compared with liver cirrhosis without HCC (62.5 ± 24.7%, from 5.1 to 96.0%, P < 0.005)." (PMID 23533353, 2013).
male infertility (2 papers, 2010 to 2020). The inability of the male to effect fertilization of an ovum after a specified period of unprotected intercourse. "Meanwhile, mouse h2ax mutant displays male infertility due to unable to form sex body, but female h2ax mouse exhibit normal meiosis." (PMID 32670319, 2020). "Interestingly, unlike MDC1 or H2AX whose deficiency only leads to male infertility, loss of BRIT1 also lead to female infertility with much smaller ovary, suggesting that BRIT1 may also function as a key regulator in oocyte meiotic recombination." (PMID 20107607, 2010).
meningioma (2 papers, 2021 to 2025). A generally slow growing tumor attached to the dura mater. "Additionally, γ-H2AX staining revealed increased DNA damage and reduced proliferation of meningioma cells in tumors from SYHA1813-treated mice." (PMID 40052125, 2025). "The expression of EPN1, EXOSC4, H2AX, and MZT2B was related to both WHO grades and age of patients and was significantly different between normal meningeal tissues and meningiomas." (PMID 35004283, 2021). "Among 32 key hub genes screened, EPN1, EXOSC4, H2AX, and MZT2B not only showed significant differences between meningioma molecular subtypes but also had the potential to be the marker genes of specific meningioma subtype." (PMID 35004283, 2021). "EPN1, EXOSC4, H2AX, and MZT2B not only showed significant differences between meningioma molecular subtypes but also had the potential to be the marker genes of specific meningioma subtypes." (PMID 35004283, 2021).
mesothelioma (2 papers, 2019 to 2022). A usually malignant and aggressive neoplasm of the mesothelium which is often associated with exposure to asbestos. "Temporal differences in γ-H2AX fluorescence intensity between low and high radiation doses may therefore suggest different cellular responses of mesothelioma cell lines to low- and high-dose radiation in our study." (PMID 36420194, 2022).
nasopharyngeal carcinoma (2 papers, 2017 to 2023). A carcinoma arising from the nasopharyngeal epithelium. "However, experiments performed in nasopharyngeal carcinoma cells, suggest that knockdown of ANXA1 inhibits DNA damage by decreasing the generation of intracellular reactive oxygen species and the formation of γ-H2AX and promotes DNA repair by increasing DNA-dependent protein kinase activity." (PMID 37373303, 2023).
Nijmegen breakage syndrome (2 papers, 2017 to 2022). Nijmegen breakage syndrome is a rare genetic disease presenting at birth with microcephaly, dysmorphic facial features, becoming more noticeable with age, growth delay, and later-onset complications such as malignancies and infections. "NBS1, which is the outcome of mutated genes in Nijmegen breakage syndrome (NBS), acts as an effector of H2AX in response-related DNA damage." (PMID 35236304, 2022). "I171V mutation locates in the BRCT domain of hNBS1 and decreases formation of γ-H2AX foci in Nijmegen breakage syndrome (NBS) cells." (PMID 28107384, 2017).
progeria (2 papers, 2020 to 2024). "Z24−/− MSCs developed increased DNA damage (γ‐H2AX+) and cellular senescence (SA‐β‐Gal+), which are consistent to the Z24−/− mice progeria phenotypes." (PMID 32710480, 2020). "Importantly, the level of γ-H2AX in the nucleus showed no obvious difference between WT and Z24−/− myofibers, suggesting that progeria-aged myofibers did not develop increased level of damage to ncDNA." (PMID 39039044, 2024).
psoriasis (2 papers, 2024 to 2025). An autoimmune condition characterized by red, well-delineated plaques with silvery scales that are usually on the extensor surfaces and scalp. "The expression of claudin, cyclin B1, cyclin D1, filaggrin, phospho-histone H2AX, kallikrein 7, Ki67, loricrin, NFAT5, and periplakin was assessed on punch biopsies obtained from eight psoriasis and six atopic eczema patients." (PMID 40559228, 2025).
renal cell carcinoma (2 papers, 2021 to 2023). "Moreover, the interference of PDIA6 increased phosphorylation of H2A histone family member X (γH2AX), while decreased Rad51 and phosphorylated DNA-dependent protein kinase (DNA-PK) (p-DNA-PK) in imatinib-resistant renal cell carcinoma cells." (PMID 34781823, 2021).
skin inflammation (2 papers, 2021 to 2024). "For UV-induced skin disorders, paeonol ameliorates SUV-induced skin inflammation by inhibiting the increase of TOPK, the phosphorylation of p38, JNKs and H2AX, and the secretion of IL-6 and TNF-α in Babl/c mouse." (PMID 35095512, 2021).
skin reaction (2 papers, 2013 to 2023). "In addition, cells from cancer patients with an adverse acute skin reaction (grade 3) to RT showed significantly increased radiation-induced γ-H2AX foci and their protracted disappearance compared to the group of BC patients with normal skin reaction (grade 0–1)." (PMID 23617930, 2013).
abdominal aortic aneurysm (1 paper, 2017). Enlargement and ballooning of the vessel that supplies arterial blood to the abdomen, pelvis and legs. "There was no change in γ-H2AX or pATM expression at any time point during the peri-operative period of open abdominal aortic aneurysm repair." (PMID 29054934, 2017).
actinic keratosis (1 paper, 2019). A precancerous lesion of the skin composed of atypical keratinocytes. "In fact, immunofluorescence analysis of surgically excised skin samples showed increased γ-H2AX levels in fibroblasts adjacent to premalignant (actinic keratosis; AK) and malignant (SCC) cancer lesions, in both of which CSL levels are decreased, relative to fibroblasts of flanking unaffected skin." (PMID 31467287, 2019).
acute leukemia (1 paper, 2023). A clonal (malignant) hematopoietic disorder with an acute onset, affecting the bone marrow and the peripheral blood.